KHDRBS1 (KH RNA binding domain containing, signal transduction associated 1)
Diseases named in the same sentence as KHDRBS1 in open-access papers (continued):
Sharing a sentence is not in itself a finding about the gene and the disease.
leukoplakia (1 paper, 2014). A white patch or plaque on a mucous membrane that cannot be characterized clinically or pathologically as any other disease. "Amplification of BTBD7, KHDRBS1, PARP1 and RAB1A was exclusively detected in progressive leukoplakia and corresponding OSCC." (PMID 24403051, 2014). "Amplified genes mapping within recurrent CNAs (KHDRBS1, PARP1, RAB1A, HBEGF, PAIP2, BTBD7) were selected for validation, by quantitative real-time PCR, in an independent set of 32 progressive leukoplakia, 32 OSSCs and 21 non-progressive leukoplakia samples." (PMID 24403051, 2014). "BTBD7, KHDRBS1, PARP1 and RAB1A were all found to be amplified in progressive leukoplakia lesions and OSSCs and not amplified in non-progressive leukoplakia." (PMID 24403051, 2014).
liver cancer (1 paper, 2024). An epithelial or non-epithelial malignant neoplasm that arises from the liver. "Consistent with OS findings, results from disease-specific survival (DSS) and disease-free interval (DFI) analyses indicated poorer disease-specific survival outcomes in liver cancer patients with high KHDRBS1 expression." (PMID 38660302, 2024). "Subsequent progression-free interval (PFI) analysis reinforced these observations, underscoring the potential of KHDRBS1 as a viable biomarker for liver cancer." (PMID 38660302, 2024). "In the overall survival (OS) analysis, elevated expression of KHDRBS1, as observed in liver cancer (LIHC), was identified as an adverse prognostic factor for patients." (PMID 38660302, 2024).
metastasis (1 paper, 2020). The spread or migration of cancer cells from one part of the body (where they first appeared) to another. "Taken together, our findings support the importance of the leptin/LEPR/KHDRBS1 axis and of adiponectin in the progression of bone metastasis and suggest their potential application in pharmacological interventions." (PMID 33213024, 2020).
oral cancer (1 paper, 2014). "Considering that the balance between cell death and survival is important in oncogenic transformation processes, assessment of KHDRBS1-RAS in oral cancer progression may be relevant to further elucidate the molecular mechanisms of oral tumorigenesis." (PMID 24403051, 2014).
premature ovarian failure (1 paper, 2025). "Since human patients with missense mutations in KHDRBS1 have premature ovarian failure, it is likely that our work has direct relevance to human fertility." (PMID 41411219, 2025).
renal clear cell carcinoma (1 paper, 2024). "Despite these findings, our pan-cancer analysis reveals an association between high KHDRBS1 expression and favorable clinical outcomes in renal clear cell carcinoma, suggesting that KHDRBS1 may not always function as an oncogene." (PMID 38660302, 2024).
X-linked hereditary ataxia (1 paper, 2024). "KHDRBS1 acts as an oncogenic splicing factor, linked to metabolic functions and diseases such as premature menopause and X-linked hereditary ataxia." (PMID 39717265, 2024).
cancer (62 papers, 2009 to 2025). A tumor composed of atypical neoplastic, often pleomorphic cells that invade other tissues. "We further investigated the association between KHDRBS1 gene expression levels and survival rates in human cancer patients." (PMID 38660302, 2024). "We conclude that rewiring of KHDRBS1 interactions in cancer is directly associated with patient prognosis." (PMID 31366900, 2019). "Notably, heightened KHDRBS1 expression significantly correlates with the activation of essential pathways implicated in cancer progression, encompassing the cell cycle, DNA replication, cellular migration, and angiogenesis." (PMID 38660302, 2024). "This dual functionality in attenuating inflammatory cytokine release while modulating tumorigenicity highlights the complex and multifaceted role of KHDRBS1 in both immunoregulation and cancer biology." (PMID 40738927, 2025). "At the genomic level, the distribution of KHDRBS1 gene copy number variations across different cancer types were delineated." (PMID 38660302, 2024). "At the epigenetic level, through pan-cancer analysis, we revealed the correlation between KHDRBS1 mRNA expression levels and DNA methylation sites across different cancer types." (PMID 38660302, 2024). "Subsequent investigations can delve into tailored therapeutic approaches targeting KHDRBS1 and validate its utility as a prognostic indicator across various cancer subtypes." (PMID 38660302, 2024). "This research elucidates the pivotal role of KHDRBS1 in HCC cancer and provides scientific groundwork for potential therapeutic strategies targeting KHDRBS1." (PMID 38660302, 2024). "The differential expression of KHDRBS1 mRNA between normal and tumor tissues was examined, revealing that in the majority of cancer types, the expression levels of KHDRBS1 mRNA were significantly elevated in tumor tissues compared to normal tissues." (PMID 38660302, 2024). "This detail accentuates the heterogeneity of KHDRBS1 involvement in cancer, emphasizing its potential as a biomarker or therapeutic target within distinct oncological contexts." (PMID 38660302, 2024). "In this study, we conducted a multi-omics analysis of the molecular characteristics of KHDRBS1 in human cancers." (PMID 38660302, 2024). "Aberrant expression of KHDRBS1 has been observed in various cancers, garnering widespread attention in cancer research." (PMID 38660302, 2024). "For each type of cancer, patients with higher KHDRBS1 expression (Z > 1) were selected for correlation analysis." (PMID 31366900, 2019). "To reconfirm our observation, we have compared the KHDRBS1 expression in healthy and cancer tissue of the same patient." (PMID 31366900, 2019). "Our study shows molecular network of KHDRBS1 is patient-specific and varies across the cancer tissue." (PMID 31366900, 2019). "Higher and lower expression is classified based on the Z-score value of KHDRBS1 expression, which is provided by TCGA for all four cancer types i.e. KIRP, LUAD, OV and LAML." (PMID 31366900, 2019). "The result indicates a positive correlation between KHDRBS1 expression status and cancer phenotype in KIRP and LUAD." (PMID 31366900, 2019). "For the first time, we have shown that expression of KHDRBS1 in all four cancers is heterogeneous and patient specific." (PMID 31366900, 2019). "This provides us the lead to do the further experiment to find the cancer-specific module in all coexpressed genes of KHDRBS1." (PMID 31366900, 2019). "We calculated the correlation of KHDRBS1 to all other genes (20531 genes) expressed in specific cancer." (PMID 31366900, 2019). "Genes with the correlation coefficient (rs) > 0.3, P < 0.05 and which have physical interaction with KHDRBS1 were screened for each cancer." (PMID 31366900, 2019). "KHDRBS1 nuclear localization and overexpression is correlated with poorly differentiated cancer cells, advanced T, N, and M1 stage." (PMID 31440515, 2019).
cancer (continued). "Based on this observation we decided to group the cancer patients depending on KHDRBS1 expression level (higher and lower expression)." (PMID 31366900, 2019). "Venn diagrams show that each cancer type has overlapping genes which are coexpressed and also physically interact with KHDRBS1." (PMID 31366900, 2019). "This indicates; in KIRP and LUAD, higher expression of KHDRBS1 possibly plays a critical role in the cancer-specific event." (PMID 31366900, 2019). "To address the patient and cancer-specific role of KHDRBS1, we performed genome-wide correlation analysis." (PMID 31366900, 2019). "Current studies also suggest that KHDRBS1 may promote cancer by influencing cell cycle regulation and enhancing tumor cell migration and invasion, consistent with our findings." (PMID 38660302, 2024). "Abnormal expression of KHDRBS1 directly impacts cancer patient prognosis." (PMID 39717265, 2024). "Moreover, the expression of KHDRBS1 mRNA was relatively stable across various cancer cell lines, albeit with some fluctuations." (PMID 38660302, 2024). "Additionally, in pan-cancer analysis, a significant positive correlation between KHDRBS1 gene copy number and KHDRBS1 mRNA expression levels was observed." (PMID 38660302, 2024). "Cytoplasmic and nuclear localization of KHDRBS1 may contribute to neoplastic transformation or tumour progression through diverse molecular mechanisms in different cancer types or cellular contexts." (PMID 33213024, 2020). "The marked expression of KHDRBS1 in the nucleus and its presence in the cytoplasm of metastatic cells suggest that KHDRBS1 can perform a wider range of functions in metastasis than in carcinoma." (PMID 33213024, 2020). "We found that expression of KHDRBS1 is highly scattered in cancer tissue in both KIRP and LUAD." (PMID 31366900, 2019). "Therefore higher and lower expression of KHDRBS1 within a particular cancer type is grouped based on Z -score of greater than 1 (higher expression) or less than −1 (low expression) respectively." (PMID 31366900, 2019). "To understand the cancer-specific behavior of KHDRBS1, we performed the genome-wide correlation analysis in all four cancers for the patients with higher expression of KHDRBS1 and screened the genes which have significant correlation and direct interaction with KHDRBS1." (PMID 31366900, 2019). "We observed a similar result in case of KHDRBS1 in the different cancer cell." (PMID 31366900, 2019). "Besides, KHDRBS1 regulates the alternative splicing of several genes, most of them involved in human cancer, such as CD44, Bcl-xl, Sgce, SMN2, SF2/ASF, and Cyclin D1." (PMID 31440515, 2019). "However, this stratification of patients in higher and lower expression based on Z-score of KHDRBS1 expression is limited to specific cancer patients within a particular cancer type." (PMID 31366900, 2019). "Furthermore, Z-score distribution also shows that there are many patients within specific cancer who have significantly high or low expression of KHDRBS1." (PMID 31366900, 2019). "We explored the molecular mechanism of KHDRBS1 to be a prognostic marker in four different cancers." (PMID 31366900, 2019). "Therefore, investigation on the interacting partners of KHDRBS1 and correlation among them could light-up exact mechanism of KHDRBS1 function in cancer." (PMID 31366900, 2019). "NCL (nucleolin) and Sam68 (KHDRBS1) belong to the category of RNA-binding proteins (RBPs), which control RNA metabolism and biogenesis—including RNA synthesis, pre-RNA splicing, RNA processing, ribosomal assembly and maturation—and play multiple roles in cancer development." (PMID 30064438, 2018). "Thus, we hypothesize that the secretion of SPP1 in regulating the HCC tumor microenvironment may be a mechanism underlying the malignant functions of KHDRBS1-positive cells, as the role of SPP1 in remodeling the tumor microenvironment has been widely reported in various cancers." (PMID 38660302, 2024).
cancer (continued). "Sam68 (KHDRBS1), a homolog of KHDRBS3, was found to be co-expressed with cancer-related genes in the genome-wide analysis." (PMID 35884586, 2022). "Genome-wide coexpression analysis reveals genes and transcripts which are coexpressed with KHDRBS1 in KIRP and LUAD, form the functional modules which are majorly involved in cancer-specific events." (PMID 31366900, 2019). "Lastly, the CCLE database revealed that the expression levels of KHDRBS1 mRNA in these cancer cell lines were also relatively stable, without significant fluctuations." (PMID 38660302, 2024). "Conversely, in the remaining three cancer types, KHDRBS1 expression did not exhibit significant variation." (PMID 38660302, 2024). "Our analysis shows that expression of KHDRBS1 within a specific cancer is heterogeneous and higher expression of KHDRBS1 does not always affects the patient survival in all cancer." (PMID 31366900, 2019). "It is observed that in all four cancers the Z -score of KHDRBS1 expression is widely distributed from negative to positive values." (PMID 31366900, 2019). "It is interesting to notice that overexpression of KHDRBS1 leads to enrichment of cancer-specific events in KIRP, LUAD but not in OV and LAML." (PMID 31366900, 2019). "Irrespective of the higher expression of KHDRBS1, the significant divergence of its biological roles and prognostic value is due to its cancer-specific interaction partners and correlation networks." (PMID 31366900, 2019). "It is noticed that the common genes, which are coexpressed and interact with KHDRBS1 are involved in the cancer-specific processes in KIRP and LUAD, but not in LAML and OV." (PMID 31366900, 2019). "In this study, we present genome-scale evidence for KHDRBS1/Sam68 to be a prognostic or non-prognostic marker in four different human cancers." (PMID 31366900, 2019). "Therefore genes which are coexpressed and interact with KHDRBS1 are mostly different in KIRP and LUAD, although they are involved in cancer-specific biological processes which are accountable for patient mortality." (PMID 31366900, 2019). "KHDRBS1 showed a larger difference in expression level when compared to PAXIP1, although differences for both genes were not statistically significant, likely due to the low number of BRCA2 mutant cancers." (PMID 30626869, 2019). "However, the expression levels of KHDRBS1 or SETD7 alone did not display any statistically significant correlation with survival rates of cancer patients." (PMID 35326563, 2022). "This suggests that KHDRBS1 expression is patient-specific and not cancer-specific." (PMID 31366900, 2019). "This indicates that the expression of KHDRBS1 mRNA is not recurrently high or low in all cancers." (PMID 31366900, 2019). "Similarly, we observed there is no observable difference of KHDRBS1 expression in cancer compared to normal." (PMID 31366900, 2019). "This gives us fascinating evidence that the over-expression of KHDRBS1 may not always be accountable for cancer progression and patient survival." (PMID 31366900, 2019). "However, we argue that higher expression of KHDRBS1/Sam68 may not be a reason for cancer phenotype in all types of tissues because cancer arises due to the perturbation of multiple genes." (PMID 31366900, 2019). "Therefore the RSEM values of KHDRBS1 mRNA Z > 1 and Z < −1 are screened for cancer tissue of four type of cancer, and non-parametric Mann-Whitney test was performed to check whether patients within Z > 1 and Z < −1 group have any significant difference in KHDRBS1 mRNA expression level." (PMID 31366900, 2019).
tumor (40 papers, 2008 to 2025). "Paradoxically, in vivo xenograft experiments revealed that KHDRBS1-deficient tumours grew more rapidly than their wild-type counterparts, suggesting a context-dependent, potentially tumour-suppressive role of KHDRBS1 in this model." (PMID 40738927, 2025). "The association between KHDRBS1 gene expression and clinical pathological characteristics, tumor immune features, and tumor-related pathways in HCC patients was extensively investigated utilizing TCGA-LIHC data." (PMID 38660302, 2024). "Our investigation unveils the association between aberrant expression of KHDRBS1 gene and tumor prognosis, yet the precise mechanisms remain elusive." (PMID 38660302, 2024). "In contrast, KHDRBS1 KO HeLa tumours in the F1F3 group exhibited significantly reduced tumour weights compared to the PBS group, indicating increased sensitivity of KHDRBS1-deficient tumours to F1F3 treatment, which was consistent with our in vitro findings." (PMID 40738927, 2025). "Further investigation is warranted to elucidate the precise signaling pathways by which KHDRBS1 orchestrates the balance between immune activation and tumour progression." (PMID 40738927, 2025). "Following F1F3 stimulation, both HeLa and KHDRBS1 KO HeLa tumours showed strong upregulation of iNOS (inducible nitric oxide synthase) and CD86, canonical markers of M1 macrophages with pro-inflammatory and antitumour." (PMID 40738927, 2025). "Mechanistically, KHDRBS1 promotes tumour growth and metastasis through Wnt/β-catenin and PI3K/Akt signalling, as well as epithelial-mesenchymal transition induction, while inhibiting apoptosis via interactions with tumour suppressor genes such as p5327,28." (PMID 40738927, 2025). "Concurrently, our analysis of the anti-tumor immune response steps also supports these findings, where high expression levels of KHDRBS1 correlate with restricted immune cell infiltration." (PMID 38660302, 2024). "Results revealed varied levels of immune activity across multiple stages in the high KHDRBS1 expression group, particularly in anti-tumor immune cycles, including recruitment and infiltration of T cells and NK cell infiltration." (PMID 38660302, 2024). "While previous findings shed light on the influence of KHDRBS1 on glycolytic metabolism in mouse neural precursor cells, its impact on tumor cell metabolism remains unexplored." (PMID 38660302, 2024). "The results of our study underscore the pivotal role of KHDRBS1 as a facilitator in tumor cell metabolic function." (PMID 38660302, 2024). "Future investigations should delve deeper into the impact of KHDRBS1 on the HCC tumor microenvironment, holding significant implications for HCC treatment." (PMID 38660302, 2024). "Subsequently, by exploring the relationship between KHDRBS1 expression and various stages of the tumor immune cycle, we further elucidated the role of KHDRBS1." (PMID 38660302, 2024). "Results suggested that the tumor carried a fusion of exons 1–8 of the KHDRBS1 gene and exons 12–17 of the NTRK1 gene." (PMID 33941195, 2021). "- KHDRBS1 nuclear localization and overexpression is correlated with poor tumor differentiation, advanced T stage, lymph node involvement, and distant metastasis." (PMID 31440515, 2019). "Moreover, both wild-type and KHDRBS1 KO HeLa tumours responded to F1F3 with increased immune cell infiltration." (PMID 40738927, 2025). "However, in the F1F3-treated KHDRBS1 KO group, tumour tissue displayed active mitoses (grey arrows) along with increased macrophage presence (blue arrows) in the peritumoral connective tissue." (PMID 40738927, 2025). "Moreover, comparison of tumour sizes in the PBS group showed that KHDRBS1 KO tumours were larger than wild-type HeLa tumours." (PMID 40738927, 2025). "Additionally, our analysis of anti-tumor immune steps revealed an association between elevated KHDRBS1 expression and immune cell infiltration suppression, suggesting a role for KHDRBS1 in modulating the HCC tumor microenvironment." (PMID 38660302, 2024).